MDM2 (MDM2 proto-oncogene)
Diseases named in the same sentence as MDM2 in open-access papers (continued):
Sharing a sentence is not in itself a finding about the gene and the disease.
lung carcinoma (continued). "However, downregulation of FOXO3 promoted DNMT3B overexpression, leading to tumor growth in lung cancer, while clinical findings also showed that there was a high DNMT3B, low FOXO3a, and high MDM2 expression associated with low survival rates in lung cancer patients." (PMID 35847844, 2022). "Thus, MDM2 (rs2279744) polymorphism does notaffect the risk of developing lung cancer." (PMID 33959694, 2020). "Our recent work examined the role of extrachromosomal DNA (ecDNA) in lung cancer and found enrichment of MDM2 amplification via ecDNA in LCINS58." (PMID 41509216, 2025). "The published article titled “miR-641 functions as a tumor suppressor by targeting MDM2 in human lung cancer” has been retracted from Oncology Research, Vol." (PMID 40109865, 2025). "MDM2 (E3 ubiquitin-protein ligase Mdm2) amplification has been identified as resistance mechanism in patients with RET-a rearranged lung cancers." (PMID 40283927, 2025). "EZH2 and MDM2 are critical in lung cancer; the activation of EZH2 accelerates cell growth, promoting rapid tumor progression and facilitating cancer cell dissemination to other organs by inducing EMT, thereby increasing cell mobility and invasiveness." (PMID 40070571, 2025). "Targeting MDM2 presents a potential strategy to combat lung cancer by disrupting its interactions or inhibiting its activity." (PMID 40070571, 2025). "It has been observed that CBX3 interacts with and potentially enhances the stability of MDM2 in lung cancer cells, inhibiting its auto-ubiquitination." (PMID 39272883, 2024). "This successful up-regulation of the DNMT3B gene, out of the complex relationship with both FOXO3a and MDM2, results in poor prognosis for lung cancer patients." (PMID 39165584, 2024). "Further research has revealed that its loss causes dysregulation of MDM2 expression through the EGFR signaling pathway, contributing to lung cancer development." (PMID 38634049, 2024). "So, we analyzed the potential association between activated p90RSK (pRSK) and MDM2 accumulation (MDM2) in primary lung cancers and melanomas." (PMID 39329730, 2024). "Numerous studies have also established the MDM2 gene’s efficacy as a prognostic biomarker in a variety of cancer types, including human lung carcinomas, cervical carcinogenesis, bladder cancer, neck cancer, and ovarian cancer, as well as glioblastoma." (PMID 37049742, 2023).
lung carcinoma (continued). "MDM2 amplification has been detected in many human malignancies, including lung cancer, colon cancer and other malignancies, and the phenomena of amplification occurs more frequently in metastatic and recurrent cancers compared to non-malignant tumors." (PMID 36837574, 2023). "miR-145-5p overexpression enhanced the radiosensitivity of resistant lung cancer cells, and its radiation target MDM2 was identified." (PMID 37569824, 2023). "MDM2 induces epithelial-mesenchymal transition by enhancing Snail expression or via activation of Smad2/3 signaling in breast and lung carcinomas." (PMID 35177036, 2022). "More recently, FLT PET-CT assessment to novel targeted therapy with a c-MET inhibitor and MDM2 inhibitor in lung cancer revealed an early response at two selected time points, namely 9 days in one participant and at 4 weeks in two other participants." (PMID 36082278, 2022). "SHANK1 bound with KL and MDM2, and downregulated KL by ubiquitin degradation, and it promoted the migration, invasion, and proliferation abilities of lung cancer cells." (PMID 35468874, 2022). "In the present study, we examined the impact of MDM2 genomic heterogeneity on early lung cancer clinical outcomes and on tumor response to therapy targeting MDM2." (PMID 35158979, 2022). "Recent studies have shown that miR-641 expression is reduced in lung cancer tissues, and miR-641 overexpression significantly inhibits the cell survival by targeting MDM2 in lung cancer cells." (PMID 35152838, 2022). "Polymorphic changes in the MDM2 gene have been identified as another reason for lung cancer, based on data collected from more than 11,638 patients." (PMID 35326902, 2022). "Many previous studies have demonstrated that aberrant MDM2 expression plays an important role in proliferation and migration of lung cancer cells." (PMID 33809929, 2021). "MDM2 overexpression then promotes the migration and invasion of lung cancer cells by interacting with MTBP." (PMID 33809929, 2021). "The present study found that LNC CRYBG3 overexpression increased MDM2 levels and led to lung cancer cell metastasis, while LNC CRYBG3 depletion suppressed MDM2 expression and metastasis." (PMID 33809929, 2021).
lung carcinoma (continued). "MiR-641 has been shown as a tumor suppressor by targeting MDM2 in human lung cancer, and a regulator of PI3K/Akt pathway in glioblastoma multiforme." (PMID 32099534, 2020). "FOXD3-AS1 and MDM2 mRNA expression were up-regulated while miR-127-3p expression was down-regulated in the lung cancer tissues in comparison with normal adjacent tissues." (PMID 32742197, 2020). "The comparison for FOXD3-AS1, miR-127-3p and MDM2 expressions was performed in lung cancer tissues and normal adjacent lung tissues." (PMID 32742197, 2020). "It has been reported that miR-641 can target MDM2 in lung cancer and serve as a tumor suppressor; miRNA-641 inhibits the growth, migration and invasiveness, prompts cervical cancer cell apoptosis via straightly targeting zeb1." (PMID 32667627, 2020). "Pine S.R., Mechanic L.E., Bowman E.D., Welsh J.A., Chanock S.C.,Shields P.G., Harris C.C. MDM2 SNP309 and SNP354 are notassociatedwith lung cancer risk." (PMID 33959694, 2020). "Clinical investigations showed the up-regulation of FOXD3-AS1 and MDM2; while down-regulation of miR-127-3p in treatment-sensitive lung cancer tissues." (PMID 32742197, 2020). "A previous study reported that USP24 can stabilize MDM2 then decrease the Suv39h1 level resulting in lung cancer metastasis." (PMID 30911287, 2019). "MDM2 amplification has been detected in many human malignancies, including lung cancer, colon cancer and other malignancies." (PMID 31440117, 2019). "Preclinical study has demonstrated the anticancer effects of small molecule MDM2 inhibitor both in A549 cells and in patient-derived lung cancer xenograft." (PMID 28074102, 2016).
lung carcinoma (continued). "For each unit increase in the relative expression of the DUSP6, GRB2, and MDM2 genes, the odds of having lung cancer increased by 7.71, 7.41 and 5.36, respectively." (PMID 27418131, 2016). "RPL37, RPS15, and RPS20 were cloned into a mammalian expression vector and transfected into H1299 lung carcinoma cells alongside Mdm2." (PMID 23874713, 2013). "To gain insight into a potential link between MDM2 and NRF2 genotypes, we have analyzed the SNP (c.309T>G) in the MDM2 gene as well as the SNP (–617C>A) in the NRF2 gene using the genomic DNA samples from lung cancer patients." (PMID 24040073, 2013). "We detected a statistically significant association between the MDM2 SNP309 polymorphism and the risk of lung cancer in females." (PMID 23170107, 2012). "In the overall analysis, using the fixed-effect model, significant associations between the MDM2 SNP309 polymorphism and lung cancer risk were observed in the recessive model (OR, 1.143; 95% CI, 1.047–1.247)." (PMID 23170107, 2012). "In conclusion, the association between MDM2 SNP309 and lung cancer was statistically significant, particularly in Asians, women and never smoking population." (PMID 23170107, 2012). "We prefer to believe that the estrogen receptor α (ERα) regulates MDM2 SNP309 expression and leads to an increased risk of lung cancer in females." (PMID 23170107, 2012). "There were 14 original studies relevant to the associated of MDM2 SNP309 polymorphism and lung cancer risk retrieved." (PMID 23170107, 2012). "Distribution of MDM2 T309G genotypes among lung cancer cases and controls included in the present meta-analysis." (PMID 22844496, 2012). "In the overall analysis, a significant association between MDM2 SNP309 polymorphism and lung cancer risk was observed (OR, 1.143; 95% CI, 1.047–1.247)." (PMID 23170107, 2012). "Subsequently, several molecular epidemiological studies were conducted to assess the association between MDM2 SNP309 and lung cancer risk in Asians Caucasians and African-Americans." (PMID 23170107, 2012). "Considering the limitations of this meta-analysis, further studies with large sample sizes, using well-designed and more accurate methods of genotyping are warranted to confirm the association between MDM2 SNP309 and lung cancer risk." (PMID 23170107, 2012). "Previous meta-analyses elucidating the link between the MDM2 SNP309 polymorphism and lung cancer risk have provided discrepant results." (PMID 23170107, 2012). "To resolve these inconsistencies, we conducted the present meta-analysis of available case-control studies investigating the association between MDM2 SNP309 and lung cancer risk using METAGEN." (PMID 23170107, 2012).
lung carcinoma (continued). "LicoA induces G2/M-phase cell cycle transition by decreasing the expression of MDM2, cyclin B1, cdc2, and cdc25c proteins, and it causes apoptosis by upregulating the activation of proapoptotic caspase-3 and PARP cleavage via ER stress in human lung cancer." (PMID 40002335, 2025). "Overall, the molecular docking analysis indicated strong binding affinities between MA and several key proteins associated with lung cancer, including EGFR, MDM2, IGF1R, EZH2, and GSK3B, with binding energies below −10.0 kJ/mol, suggesting exceptional binding strength." (PMID 40070571, 2025). "Therefore, Hoiamide D, as an important natural product and MDM2 inhibitor, deserves further research to explore its potential for improving lung cancer treatment." (PMID 38741108, 2024). "For MDM2 rs2279744 (309T>G) (n = 4), two studies in lung cancer patients observed a protective effect for grade 3-4 thrombocytopenia (OR = 0.472; 95% CI: 0.257–0.866; p = 0.015) and grade 3-4 neutropenia (OR = 0.27; 95% CI: 0.08763–0.8859; p = 0.030) respectively." (PMID 39234108, 2024). "Therefore, blocking MDM2-mediated TOP2β degradation by RG7112 synergistically suppresses lung cancer cell survival following treatment with VP-16, resulting in an increase in apoptosis and susceptibility to VP-16 treatment." (PMID 38263255, 2024). "Our study suggests that MDM2 amplification/overexpression can be investigated as a clinical biomarker to target lung cancer patients who may benefit from MDM2-targeted therapy." (PMID 35158979, 2022). "BABAM2 formed a complex with endogenously expressed MDM2 in lung cancer cells." (PMID 34975328, 2022). "Overexpression of MDM2 is the most common change, especially in patients with lung cancer." (PMID 36551770, 2022). "Moreover, luciferase reporter assays showed that eEF1A1 directly targets the MDM2 promoter region in lung cancer cells and that LNC CRYBG3 has a high affinity for the binding of eEF1A1 to the MDM2 promoter." (PMID 33809929, 2021). "Interestingly, the MDM4 inhibitor, SJ‐172550, and the MDM2 inhibitor, nutlin‐3, showed a synergistic effect with erlotinib in erlotinib‐resistant lung cancer cell lines, NCI‐H820 and NCI‐H1975." (PMID 33188726, 2021). "MDM2 is amplified in about 3.7% of all cancers, including ∼4% of lung cancers and ∼8% of GBM." (PMID 34481841, 2021). "MDM2 protein expression may also be used to evaluate the malignancy grade and prognosis of patients with lung cancer." (PMID 33968713, 2021). "In the factorial stratification analysis, the MDM2 rs2279744 polymorphism was statistically significantly associated with lung cancer among the nonsmokers (OR (95% CI) = 1.334 (1.125–1.581), P = 0.001)." (PMID 32513119, 2020).